HDAC1 (histone deacetylase 1)
Diseases named in the same sentence as HDAC1 in open-access papers (continued):
Sharing a sentence is not in itself a finding about the gene and the disease.
Alzheimer disease (21 papers, 2017 to 2025). A progressive, neurodegenerative disease characterized by loss of function and death of nerve cells in several areas of the brain leading to loss of cognitive function such as memory and language. "For example, in Alzheimer’s disease (AD), HDAC1 deficiency impairs the repair of oxidative DNA lesions, leading to neuronal DNA damage and cognitive decline." (PMID 41388741, 2025). "Pharmacological activation of HDAC1 with exifone attenuates 8-oxoG repair in old wild-type mice and in a model of Alzheimer’s disease, while HDAC1 deficiency has the opposite effect." (PMID 32599754, 2020). "Furthermore, HDAC1 serves a protective role in neurons, and HDAC1 function loss has been identified in CDK/p25‐induced neurodegenerative conditions including Alzheimer's disease and stroke." (PMID 32449313, 2020). "Compound 5104434, a selective enzymatic reactivator of HDAC1 previously reported to exert beneficial effects in Alzheimer’s disease and experimental stroke models, was evaluated for its therapeutic efficacy in post-ischemic recovery." (PMID 41388741, 2025). "In Alzheimer’s disease, overexpression of HDAC1 represses the genes involved in DNA repair and neuronal survival, while impaired Nrf2 activity exacerbates oxidative neuronal damage and neuroinflammation." (PMID 40650264, 2025). "For example, specifically promoting HDAC1 activity with pharmacological SIRT1 activators or by increasing HDAC1 function via genetic overexpression can reduce DNA damage in mouse models of Alzheimer's disease and ischemia." (PMID 32449313, 2020). "Histone deacetylase (HDAC), associated to community 22, confirms the known involvement of HDAC1 in both cancer and Alzheimer’s disease." (PMID 31247897, 2019). "Recently, histone deacetylase 1 (HDAC1) was shown to be involved in oxidative DNA damage in brain ageing and Alzheimer’s disease (AD), with mice lacking HDAC1 displaying age-associated DNA damage accumulation and cognitive impairment." (PMID 37354261, 2023). "Moreover, we observe elevated 8-oxoG along with reduced HDAC1 activity and downregulation of a similar gene set in the 5XFAD mouse model of Alzheimer’s disease." (PMID 32424276, 2020). "Remarkably, this study showed that a lentivirus-driven HDAC1::SUMO translational fusion protein could rescue the learning and memory deficits of an APP/Presenilin 1 murine model of Alzheimer's disease, suggesting that HDAC1 SUMOylation may be neuroprotective in response to Aβ accumulation." (PMID 34003109, 2021). "Moreover, PIAS1 could exert neuroprotection in hippocampus of mice with Alzheimer’s disease through SUMOylation of HDAC1." (PMID 34857740, 2021). "Noteworthy in this respect are the findings from a comparative study of Alzheimer’s disease and AMD donors that showed that HDAC1, 2, 5, and 6 expression decreased in the retina and frontal cortex of affected individuals." (PMID 32984320, 2020). "However, JUN, HDAC1, SP1, and STAT3 are also indispensable in the neuronal apoptosis mechanism of patients with Alzheimer's disease." (PMID 34992508, 2021). "Moreover, analysis of the GSE48350 dataset confirmed similar changes in HDAC1, CDC42 and YES1 expression in Alzheimer's disease, thereby providing a molecular connection between aging and Alzheimer's disease (AD)." (PMID 30341976, 2018). "Deletion of HDAC1 and HDAC2 in microglia (but not other cell types) reduces amyloid load and improves cognitive function in Alzheimer’s disease models by enhancing microglial amyloid phagocytosis." (PMID 40940748, 2025).
osteosarcoma (20 papers, 2008 to 2025). A usually aggressive malignant bone-forming mesenchymal neoplasm, predominantly affecting adolescents and young adults. "Whereas in primary osteosarcoma, cells showed a high expression of HDAC1 and 2, low levels of HDAC1 were associated with the presence of initial metastasis." (PMID 33194754, 2020). "In one study, HDAC1/2-associated immediate histone hypoacetylation occurred after laser microirradiation of a human osteosarcoma cell line to promote NHEJ, which was followed by hypoacetylation to enhance HR and guard genome integrity, supporting our hypothesis." (PMID 26683361, 2016). "HDAC1 can promote the proliferation and invasion of osteosarcoma cells by inhibiting the transcription of the MicroRNA-326 gene." (PMID 38297292, 2024). "Our result suggested the biological and therapeutic significance of TOP2A and HDAC1 in osteosarcoma." (PMID 37457661, 2023). "Our multiomic data further indicated that TOP2A and HDAC1 played critical roles in osteosarcoma through different analysis." (PMID 37457661, 2023). "High expression of HDAC1 was confirmed at transcriptional and protein levels in osteosarcoma compared with adjacent normal tissues." (PMID 37457661, 2023). "Different patterns of HDAC1 have been established as prognostic marker in osteosarcoma." (PMID 33194754, 2020). "Interestingly, only TOP2A and HDAC1 were in the shared gene list of the previously identified 139 TSGs by transcriptomic and proteomic analysis, the 54 hub‐genes and the 282 target genes of effective drugs in osteosarcoma." (PMID 37457661, 2023). "Consistent with the network pharmacology results, the RT-PCR experiments showed significant downregulation of JUN, HSP90AA1, HDAC1, and CDK1 expression by TGT, highlighting their potential significance as targets in the anti-osteosarcoma mechanism of TGT." (PMID 38297292, 2024). "To validate interactions and physical closeness of HDAC1 and NOTCH1 proteins in cells using an additional approach, we performed in situ proximity-based ligation assay (PLA) in human SJSA-1 osteosarcoma cells." (PMID 38043798, 2024). "By suppressing the activities of JUN, HSP90AA1, HDAC1, and CDK1, TGT can impede the growth of osteosarcoma cells." (PMID 38297292, 2024). "More interestingly, the multiomic analysis pointed out the pivotal role of HDAC1 and TOP2A in osteosarcoma." (PMID 37457661, 2023). "Another most interesting observation in our study is that a few of the hub genes of Rb tumors including CDK1, CDK2, CCNB1, HDAC1 and UNC5D are reported to play a key role in the pathogenesis of osteosarcoma, the most common secondary cancer in Rb patients." (PMID 35359459, 2022). "We have demonstrated that 4SC-202 inhibits osteosarcoma cell growth in vitro and in vivo, and advanced our understanding of the key roles of HDAC1, HDAC2, and HDAC3 in the biological behaviors of osteosarcoma." (PMID 34439353, 2021). "Notably, HDAC1 emerged as a hub protein, which was verified in the public database GSE33383 by comparing the expression level of MSCs with that of high-grade osteosarcoma prechemotherapy biopsy." (PMID 40989695, 2025). "We observed that HDAC1 and DNMT1 expressions remained similar independently by treatments indicating that they have no key role in the processes of acetylation and methylation in osteosarcoma." (PMID 30509303, 2018).
lung adenocarcinoma (18 papers, 2013 to 2025). A carcinoma that arises from the lung and is characterized by the presence of malignant glandular epithelial cells. "On the contrary, high expression of HDAC1 has been linked with poor prognosis in patients with lung adenocarcinoma." (PMID 28397399, 2017). "As expected, HDAC1 more strongly associated with the E-cadherin promoter in cells overexpressing wild-type Slug and Ubc9 than in Slug5M and Ubc9; and this result was also re-confirmed in human lung adenocarcinoma cell line, Hop62." (PMID 30612578, 2019). "In another study, it was found that HDAC1 mRNA expression was upregulated in non-small cell lung cancer and was associated with a low differentiated grade tumour, while lung adenocarcinoma with upregulated HDAC1 mRNA expression was associated with poor prognosis." (PMID 28410237, 2017). "SUZ12-mediated H3K27me3 modification inhibits HDAC1 expression, and modulate docetaxel resistance in lung adenocarcinoma to." (PMID 40949882, 2025). "Additional competition assays performed in lung adenocarcinoma cell A549 lysate also identified HDAC1, HDAC2, and HDAC6 as targets." (PMID 37322067, 2023). "Considering that overexpression of the epigenetic modifiers HDAC1 and HDAC3 is associated with a poor prognosis in lung adenocarcinoma, Vorinostat looks to be a promising therapeutic option." (PMID 37710391, 2023). "In our previous study, we demonstrated that HDAC1/4-mediated silencing of microRNA-200b (miR-200b) enhances docetaxel (DTX)-resistance of human lung adenocarcinoma (LAD) cells." (PMID 35864549, 2022). "We further identified that HDAC1 robustly interacts with EGFR in lung adenocarcinoma cell lines, as well as HEK293T cells, by the high-confidence K-CLASP technique and co-immunoprecipitation." (PMID 33976119, 2021). "EGFR and HDAC1 were present in the membrane-bound organelle and nuclear fractions of lung adenocarcinoma cell lines." (PMID 33976119, 2021). "In summary, this study uncovered a previously uncharacterized interaction of EGFR with HDAC1 in lung adenocarcinoma cell lines." (PMID 33976119, 2021). "Using a general phosphotyrosine cocktail antibody, we detected that endogenous HDAC1 is indeed modified by tyrosine phosphorylation in lung adenocarcinoma cell lines." (PMID 33976119, 2021). "Here we found that HDAC1-EGFR interaction patterns change in lung adenocarcinoma cell lines with different EGFR backgrounds, albeit to varying extents." (PMID 33976119, 2021). "We demonstrate that inhibition of EGFR kinase activity reduces the tyrosine phosphorylation and protein levels of HDAC1 in Gefitinib-sensitive lung adenocarcinoma cells." (PMID 33976119, 2021). "Enhancer of zeste homolog 2 and HDAC1 mRNA expression in two lung adenocarcinoma (LUAD) datasets (MDACC and TCGA) were correlated with patient outcomes." (PMID 31456359, 2019). "HDAC1 exhibited high expression in lung adenocarcinoma tissue compared to normal lung tissue." (PMID 39075515, 2024). "By way of contrast, with the treatment of HDAC1 inhibitor, VGF expression is induced in lung adenocarcinoma cells." (PMID 38528565, 2024). "Phosphorylation of the Tyr72 site on HDAC-1 promotes the antiapoptotic function of HDAC-1 and resistance to gefitinib in lung adenocarcinoma." (PMID 36263432, 2022). "More interestingly, in lung adenocarcinoma, a histological subtype of NSCLC, high HDAC1 expression has been correlated with poor prognosis, a lower differentiation grade, and reduced five-year disease-free survival rate." (PMID 33976119, 2021).
neuroblastoma (18 papers, 2012 to 2025). Neuroblastoma (NB) is the most common solid, extracranial childhood tumor. "High expression of HDAC1 mRNA is associated with multidrug resistance in the neuroblastoma cell lines." (PMID 33170151, 2020). "This direction of the correlation with DNA damaging agents is consistent with previously reported benefit of diminished HDAC1 expression in neuroblastoma cell lines, which increased their sensitivity to etoposide." (PMID 38369747, 2024). "SNORA50C contributed to cell growth and migration through the HDAC1-mediated pathway in neuroblastoma, where its depletion suppressed tumor cell proliferation, invasion and migration." (PMID 38741178, 2024). "Functionally, selective knockdown of HDAC1 sensitized the multi-drug resistant CHLA-136 cell line to etoposide, a topoisomerase II inhibitor commonly used for the treatment of high-risk neuroblastoma." (PMID 33117806, 2020). "RNA expression analysis across a large panel of neuroblastoma cell lines further demonstrated that significantly higher HDAC1 mRNA levels were present in multi-drug resistant lines compared to drug-sensitive lines." (PMID 33117806, 2020). "In neuroblastoma cells translocation of HDAC1 was reported to the cytoplasm in response to HSV-1 viral infection." (PMID 30380112, 2019). "Therefore, SNHG1 may interplay with HDAC1/2 and coordinately mediate the transition of neuroblastoma cell fate." (PMID 36130928, 2022). "A previous study showed that binding of HDAC1 to the NEP promoter and TTR promoter was decreased in neuroblastoma cells expressing the APP695 isoform." (PMID 32950104, 2021). "Indeed, both LY294002 and rapamycin significantly enhanced entinostat-mediated effects on cell viability, suggesting that HDAC1–3 inhibitors, but not HDAC8 inhibitors, cooperate with PI3K/mTOR inhibitors in our neuroblastoma MYCN-driven model." (PMID 29515255, 2018).
non-small cell lung carcinoma (17 papers, 2012 to 2025). A group of at least three distinct histological types of lung cancer, including non-small cell squamous cell carcinoma, adenocarcinoma, and large cell carcinoma. "It is reported that HDAC1 can be used as a biomarker for the efficacy and prognosis of platinum-based drugs in patients with non-small cell lung cancer." (PMID 39075515, 2024). "As a tumor suppressor, exosome-derived miR-2682-5p can inhibit the viability and migration of non-small-cell lung cancer cells and promote apoptosis through the HDAC1/ADH1A axis." (PMID 35465266, 2022). "Furthermore, more HDAC1 was recruited to enhance the transcriptional inhibitory activity of Slug, resulting in a decrease in the expression of target genes downstream of Slug, thereby promoting the metastasis of non-small cell lung cancer." (PMID 34345216, 2021). "Our study has first revealed that PHF12 interacts with HDAC1 to regulate EGFR/AKT signaling pathway and promote proliferation in non-small cell lung cancer." (PMID 39075515, 2024). "have reported that miR-2682-5p in non-small cell lung cancer (NSCLC) exosomes can inhibit the viability and migration of NSCLC cells and promote cell apoptosis through the HDAC1/ADH1A axis." (PMID 36727049, 2022). "Inhibition of HDAC1 and HDAC2 enhanced the radiosensitivity of non-small cell lung cancer." (PMID 24650256, 2014).
schizophrenia (17 papers, 2015 to 2025). A major psychotic disorder characterized by abnormalities in the perception or expression of reality. "Upregulation of HDAC1 has been found in the prefrontal cortex of patients with schizophrenia and overexpression of this enzyme seems to ameliorate the fear extinction learning cognitive function in mice." (PMID 36675131, 2023). "Increased histone deacetylase (HDAC1) enzyme activity has been observed in the frontal cortex, hippocampus, and medial temporal lobe of schizophrenia patients." (PMID 34299291, 2021). "Conversely, the hippocampi of schizophrenia-like animals showed H3K9 deacetylation that was regulated by an increase in both HDAC1 and HDAC3." (PMID 28300292, 2018). "Some previous studies have reported increased histone deacetylase (HDAC1) expression in postmortem brain samples from patients with schizophrenia." (PMID 29514709, 2018). "We observed that the hippocampi of schizophrenia-like rats had very low levels of H3K9 acetylation but displayed increases in both HDAC1 and HDAC3 levels (d1–d3)." (PMID 28300292, 2018). "Administration of an HDAC inhibitor ameliorated these phenotypes, suggesting that HDAC1 inhibition could be a therapeutic approach for schizophrenia." (PMID 39335492, 2024). "In addition, mice subjected to ELS exhibited an increased HDAC1 level in blood samples, and this effect was also observed in blood samples from patients with schizophrenia who had experienced ELS." (PMID 39335492, 2024). "Another study identified high amounts of HDAC1 mRNA and protein in the prefrontal cortex and blood of people with schizophrenia, demonstrating a relationship between HDAC1 overexpression and schizophrenia that can be regulated by butyrate produced by gut microbes." (PMID 37232729, 2023). "Importantly, Hdac1 blood levels were also increased specifically in patients with schizophrenia who had been exposed to ELS as compared with patients with schizophrenia who didn’t suffer ELS." (PMID 38107777, 2023). "Similarly, high levels of HDAC1 mRNA and protein have been found in the PFC and blood of schizophrenia patients, indicating a link between HDAC1 overexpression and schizophrenia that can be controlled by butyrate produced by gut microorganisms." (PMID 34299291, 2021). "In contrast, inducing the si-RNA-mediated knockdown of HDAC1 or the pharmacological inhibition of HDAC1 impaired learning and increased cell death, and these results correspond rather well with our observations in the OBs, in which schizophrenia-like phenotype led to the depletion of HDAC1 (b2)." (PMID 28300292, 2018). "In a murine model of early life stress (ELS) exhibiting a schizophrenia-like phenotype, an increase in HDAC1 expression across several brain regions has been documented, with this alteration correlating with similar findings in both the blood and prefrontal cortex of schizophrenia patients." (PMID 39900676, 2025). "Therefore, HDAC1 inhibition should be considered a therapeutic approach for treating schizophrenia." (PMID 39335492, 2024). "Epigenetic processes, including histone and DNA methylation, have been associated with schizophrenia through candidate gene regulation (HDAC1, GAD67) and epigenome-wide studies, lending support to the investigation of epigenetic modifications in schizophrenia." (PMID 37881537, 2023). "Some of these findings are: altered expression of various enzymes, such as increased expression of histone methyltransferases (HMT), histone deacetylase 1 (HDAC1), and reduced expression of HDAC2 in prefrontal cortex (PFC) of schizophrenia subjects." (PMID 34930904, 2021). "Elevated levels of HDAC1 in the prefrontal cortex (PFC) and hippocampus has been observed in postmortem brain tissues of schizophrenia patients." (PMID 34299291, 2021). "Together, the results indicate that co-regulation of H3K9ac by HDAC1 and HDAC3 is important to both embryonic brain development and neuro-differentiation as well as the pathophysiology of a schizophrenia-like phenotype." (PMID 28300292, 2018).